TXLNB (taxilin beta)
Description:
Promotes motor nerve regeneration (By similarity). May be involved in intracellular vesicle traffic.
Synonyms: C6orf198; MDP77; DKFZp451A175; dJ522B19.2; LST001
Tractability: PROTAC: ubiquitination databases record sites on it.
Gene: Protein-coding gene on chromosome 6 (139,239,083 to 139,291,998, reverse strand). Ensembl gene ENSG00000164440.
Gene Ontology:
Molecular function: protein binding
Cellular component: cytoplasm
Genetic constraint (gnomAD): Loss-of-function variants: 31 observed, 49.06 expected, observed/expected ratio (o/e) 0.63, 90% interval 0.47 to 0.85. The upper end of that interval is the gene's LOEUF score, 0.85, which puts it in group 3 of 6, group 1 being the genes least tolerant of losing a copy. Missense variants: 780 observed, 777.61 expected, observed/expected ratio (o/e) 1, 90% interval 0.94 to 1.06. Synonymous variants: 277 observed, 296.69 expected, observed/expected ratio (o/e) 0.93, 90% interval 0.85 to 1.03.
Homologues: Orthologues: chimpanzee TXLNB (98% identical), macaque TXLNB (95% identical), dog TXLNB (81% identical), pig TXLNB (78% identical), rabbit TXLNB (76% identical), rat Txlnb (73% identical), mouse Txlnb (72% identical), guinea pig TXLNB (69% identical), tropical clawed frog txlnb (48% identical), zebrafish txlnba (43% identical), zebrafish txlnbb (37% identical), Drosophila melanogaster CG5886 (23% identical), and 1 more. Paralogues in human: TXLNA (39% identical), TXLNG (33% identical).